SEMA4F (ssemaphorin 4F)
Description:
Probable cell surface receptor that regulates oligodendroglial precursor cell migration (By similarity). Might also regulate differentiation of oligodendroglial precursor cells (By similarity). Has growth cone collapse activity against retinal ganglion-cell axons (By similarity).
Synonyms: SEMAM; SEMAW; M-SEMA; PRO2353; S4F; m-Sema-M
Tractability: Antibody: UniProt places it where antibodies can reach, with high confidence; its Gene Ontology location is reachable by antibodies, with high confidence; UniProt predicts a signal peptide or a membrane-spanning region. PROTAC: ubiquitination databases record sites on it; its protein half-life has been measured.
Gene: Protein-coding gene on chromosome 2 (74,654,226 to 74,690,634, forward strand). Ensembl gene ENSG00000135622.
Subcellular location: Cell membrane; Postsynaptic density; Perikaryon; Cell projection, dendrite
Pathways (Reactome):
Signal Transduction: RND3 GTPase cycle
Gene Ontology:
Molecular function: protein binding; chemorepellent activity; neuropilin binding; semaphorin receptor binding
Biological process: axon guidance; cell-cell signaling; negative chemotaxis; nervous system development; neural crest cell migration; positive regulation of cell migration; semaphorin-plexin signaling pathway
Cellular component: endoplasmic reticulum; membrane; perikaryon; plasma membrane; postsynaptic density; dendrite; glutamatergic synapse; postsynaptic density membrane; postsynaptic membrane; synapse
Genetic constraint (gnomAD): Loss-of-function variants: 50 observed, 76.72 expected, observed/expected ratio (o/e) 0.65, 90% interval 0.52 to 0.82. The upper end of that interval is the gene's LOEUF score, 0.82, which puts it in group 3 of 6, group 1 being the genes least tolerant of losing a copy. Missense variants: 932 observed, 1,037.8 expected, observed/expected ratio (o/e) 0.9, 90% interval 0.85 to 0.95. Synonymous variants: 417 observed, 415.28 expected, observed/expected ratio (o/e) 1, 90% interval 0.93 to 1.09.
Homologues: Orthologues: chimpanzee SEMA4F (99% identical), macaque SEMA4F (98% identical), dog SEMA4F (93% identical), rat Sema4f (91% identical), mouse Sema4f (91% identical), pig SEMA4F (91% identical), guinea pig SEMA4F (91% identical), rabbit SEMA4F (88% identical). Paralogues in human: SEMA4C (33% identical), SEMA4B (32% identical), SEMA4G (32% identical), SEMA4D (30% identical), SEMA4A (29% identical), SEMA3G (27% identical), SEMA3D (26% identical), SEMA3B (26% identical), SEMA3A (26% identical), SEMA3F (26% identical), SEMA3E (25% identical), SEMA5B (25% identical), and 7 more.
Diseases named in the same sentence as SEMA4F in open-access papers:
SEMA4F is named in the same sentence as 17 diseases in open-access papers, as found by Europe PMC text mining. Sharing a sentence is not in itself a finding about the gene and the disease. The quoted sentences say what the papers report.
prostate carcinoma (7 papers, 2020 to 2026). A carcinoma that arises from epithelial cells of the prostate gland. "SEMA4F is a membrane-bound glycoprotein of the signaling element receptor family that has been linked to cancer in prior research, including being associated to breast cancer development, axonogenesis and neurogenesis in prostate cancer, and glioma prognosis." (PMID 36212450, 2022). "Thus, SEMA4F encoding semaphorin 4F plays a role in axonal growth cone guidance and induction of neurogenesis in prostate cancer." (PMID 35574316, 2022). "Interestingly, Sema4F-driven perineural invasion of prostate cancer cells, associated with tumor progression, highlighted another potentially important aspect of their activity in this context, deserving further studies." (PMID 33537086, 2021). "TGFB1 has diverse roles in tumor biology, including neuronal development and survival, while SEMA4F has been shown to regulate neurogenesis and axonogenesis in prostate cancer." (PMID 40805163, 2025). "SEMA4F has been described to correlate, if overexpressed, with increased motility of cells, increased invasion and disease aggressiveness in prostate cancer." (PMID 32899940, 2020). "The emaphorin4F (SEMA4F), a kind of axon‐guidance factor, overexpressed in prostate cancer cells, could enhance the ability of prostate cancer cells to induce neurite outgrowth." (PMID 41556039, 2026). "Notably, Sema4F expression in prostate cancer cells is independently predictive of tumor recurrence." (PMID 33537086, 2021). "Clinical analyses demonstrated that SEMA4F expression levels significantly correlate with both intratumoral nerve density and the extent of PNI in prostate cancer." (PMID 41556039, 2026).
glioma (5 papers, 2022 to 2025). A benign or malignant brain and spinal cord tumor that arises from glial cells (astrocytes, oligodendrocytes, ependymal cells). "Recent reports have identified the SEMA4F gene as being associated with brain network hyperactivity, correlated with enhanced glioma progression and infiltration." (PMID 40345526, 2025). "On the other hand, glioma cell SEMA4F knockdown resulted in reduced infiltration and longer survival in preclinical studies." (PMID 40345526, 2025). "In vivo models show that overexpression of the SEMA4F in glioma cells leads to enhanced infiltration and shorter survival." (PMID 40345526, 2025). "Surprisingly, severing the interhemispheric connections inhibits the activity-dependent acceleration of infiltration observed in intact controls, while mechanistic investigations identify Semaphorin 4F (SEMA4F) as a key mediator linking remote neuronal activity to glioma progression." (PMID 41018101, 2025). "Additionally, neuronal activity in brain regions contralateral to the primary tumor promotes glioma cell migration via semaphorin 4F (SEMA4F), demonstrating how remote neuronal cues can orchestrate tumor spread." (PMID 40685688, 2025).
breast carcinoma (3 papers, 2022 to 2023). "Axonogenesis is linked to tumor progression and contributes to breast cancer metastasis and we observed that both silencing of Platr18 and Sema4F abrogate metastasis to the lungs." (PMID 34810279, 2022). "Furthermore, RNA-seq analysis of human hepatocellular carcinoma (HepG2) cells silenced for hnRNP E1 and from murine 4T1 breast cancer cells treated with TGFβ also showed neuron-related factor enrichment, although these models do not display regulation for Platr18/Sema4F." (PMID 34810279, 2022).
endometrial cancer (2 papers, 2022 to 2023). Primary or metastatic malignant neoplasm involving the endometrium (mucous membrane that lines the endometrial cavity). "Further, CHRM2, GRIN1, L1CAM, and SEMA4F were found to be significantly associated with clinical stage, immune infiltration, immune response, and important signaling pathways in endometrial cancer." (PMID 36212450, 2022). "Finally, from the set (d), SEMA4F has been found to be associated with endometrial cancer." (PMID 37862362, 2023). "We propose that SEMA4F is a key regulator of tumor growth, angiogenesis, migration, and apoptosis and that it plays a role in endometrial cancer." (PMID 36212450, 2022).
breast tumor (1 paper, 2022). "Because Sema4F silencing in NMuMG-E1KD cells and blockade of TGFβ signaling in 4T1 cells does not impact tumor growth in vivo, it constitutes appropriate and unbiased model to validate the pro-neurogenic role of TGFβ in primary breast tumors." (PMID 34810279, 2022).
dyslexia (1 paper, 2017). A learning disorder characterized by an impairment in processing written words. "In addition to cancers, the SEMA4F gene has also been suggested to be involved in pulmonary tuberculosis and dyslexia." (PMID 29233967, 2017).
lymphoma (1 paper, 2023). A malignant (clonal) proliferation of B- lymphocytes or T- lymphocytes which involves the lymph nodes, bone marrow and/or extranodal sites.
melanoma (1 paper, 2021). A malignant, usually aggressive tumor composed of atypical, neoplastic melanocytes. "At protein level, several semaphorins, plexins and neuropilins have been detected in tissue cancer available in the database, including melanoma, except for Sema4A, Sema4F, Sema4G, Sema6B, plexinA4, plexinB3 for which melanoma specimens resulted weakly positive or prevalently negative." (PMID 33858502, 2021).
neuroblastoma (1 paper, 2022). Neuroblastoma (NB) is the most common solid, extracranial childhood tumor. "The role of Platr18/Sema4F in EMT-induced axonogenesis was further validated in the mouse neuroblastoma Neuro2AGTP+ coculture model." (PMID 34810279, 2022).
Stroke (1 paper, 2012). Sudden impairment of blood flow to a part of the brain due to occlusion or rupture of an artery to the brain. "Specific changes related to tissue remodeling and cell migration observed in the core and the PI areas included SEMA3A and SEMA4F (downregulated 24 h after stroke in the PI area)." (PMID 23284893, 2012).
cancer (11 papers, 2017 to 2025). A tumor composed of atypical neoplastic, often pleomorphic cells that invade other tissues. "The study also found that cancer cells induce neurite outgrowth and axon hyperplasia by secreting the axon guidance molecule semaphorin 4F (SEMA4F), and that silencing SEMA4F inhibits experimental neurogenesis." (PMID 38334648, 2024). "Furthermore, Sema4F is involved in the interaction between cancer cells and fibroblasts, promoting the migration of cancer cells along fibers." (PMID 40092993, 2025). "SEMA4F regulates embryologic axon guidance and cancer-induced neurogenesis." (PMID 37760841, 2023). "Due to its activity to induce axonogenesis and perineural cancer cell invasion, Sema4F may also represent a potential target to inhibit PC progression." (PMID 33537086, 2021). "Over-expression of Semaphorin-4F (Sema4F) in PRAD cells contributes to the communication between nerve fibers and cancer cells and induces the proliferation and migration of PRAD cells." (PMID 36900158, 2023).
tumor (9 papers, 2018 to 2025). "The findings imply that the genes CHRM2, GRIN1, L1CAM, and SEMA4F in EC have pro- or oncogenic effects as a result of the combined activity of several signaling pathways influencing tumor growth." (PMID 36212450, 2022). "The SEMA4D and SEMA4F expression was seen in 100% of the human tumor cells, albeit at low intensity." (PMID 35570846, 2022). "Beyond the specific context of the Platr18/Sema4F axis, we describe herein a novel role for TGFβ as regulator of primary tumor axonogenesis and link this new biological function to its well-described role as a regulator of later stages of tumor progression." (PMID 34810279, 2022). "Transcriptome signature analysis of cells modulated for Platr18, hnRNP E1, or treated with TGFβ revealed semaphorin-4F (Sema4F) as the most regulated transcript by Platr18 overexpression itself and one of the most modulated RNAs during tumor cell EMT in general." (PMID 34810279, 2022). "Beyond Sema4F, multiple axon-related molecules, classified for their function in tumor axonogenesis, such as Bmp7, Robo1, Fibronectin, or Nrp1, and the synaptic adhesion molecule IGSF11/VSIG-3 are regulated upon TGFβ−mediated EMT induction, hnRNP E1 silencing, or Platr18 overexpression." (PMID 34810279, 2022). "In addition, previous studies suggested that ITGB5 and IL18 are related to tumor invasiveness, whereas CXCL1 and SEMA4F are associated with cell proliferation." (PMID 31118022, 2019). "We did not observe significant impact of Sema4f silencing in tumor cell proliferation, primary tumor growth." (PMID 34810279, 2022).
SEMA4F also shares sentences with these, for which no sentence is quoted: hepatocellular carcinoma (2 papers); Alzheimer disease (1); medulloblastoma (1); Parkinson disease (1); pulmonary tuberculosis (1).